SOX9 (SRY-box transcription factor 9)
Diseases named in the same sentence as SOX9 in open-access papers (continued):
Sharing a sentence is not in itself a finding about the gene and the disease.
gastric cancer (continued). "Circ_0032821 was also highly expressed in OXA-resistant GC cells and contributes to oxaliplatin (OXA) resistance of gastric cancer cells by regulating SOX9 via miR-515-5p." (PMID 36059637, 2022). "SOX9 expression is significantly increased in Helicobacter pylori–positive gastric biopsies and its expression is required for bacteria-induced gastric cancer cell proliferation in a Wnt/β-catenin pathway dependent manner." (PMID 35221802, 2022). "In gastric cancer, circ_0032821 competitively interacts with miR-515-5p to control SRY-box transcription factor 9 (SOX9) expression." (PMID 35055115, 2022). "illustrated the oncogenic function of SOX9 in gastric cancer by enhancing EMT through the Hippo-YAP pathway." (PMID 35201494, 2021). "For example, lncRNA THOR can directly bind to the 3′UTR of SOX9, thereby enhancing SOX9 mRNA stability, and promote the stemness of gastric cancer cells and osteosarcoma cells." (PMID 33469161, 2021). "For example, SNHG14 promoted cell migration, invasion, proliferation and resistance to cell apoptosis in gastric cancer via miR-145/SOX9 axis." (PMID 33485374, 2021). "Research indicated that the level of miR-105 was low in gastric cancer tissues and cells, and SOX9 was expressed highly in gastric cancer cells." (PMID 34299149, 2021). "Conversely, miR-105 was downregulated in gastric cancer tissues, and its overexpression inhibited cell migration, invasion, and EMT in gastric cancer by targeting SOX9." (PMID 34957087, 2021). "We found that SOX9 activity impacts on cell viability and influences cell proliferation in differentiated pancreatic, glioblastoma and gastric cancer cells." (PMID 31941916, 2020). "For gastric cancer, SOX9 was identified as a critical determinant in the control of epithelial-to-mesenchymal transition (EMT) and metastasis via affecting MMP-2 and MMP-9." (PMID 33076370, 2020). "In clinical samples, SOX9 expression is elevated in glioblastoma, pancreatic ductal adenocarcinoma, gastric cancer, colon, skin or breast cancer samples respect to adjacent normal tissue." (PMID 31941916, 2020). "In a previous study, SOX9 was significantly upregulated in specimens infected with H. pylori to increase levels of β-catenin, induce gastric cancer cell proliferation, and enhance stem cell-like properties." (PMID 33362856, 2020). "For instance, COL10A1 promotes invasion and metastasis in gastric cancer through transcriptional regulation of SOX9 and the involvement of the TGF-β signaling pathway." (PMID 31992202, 2020). "In particular, we silenced SOX9 expression in cell lines of gastric cancer (AGS and MKN45), pancreatic cancer (Panc-1 and RWP-1) and glioblastoma (U373 and U251), which exhibit high SOX9 expression levels." (PMID 31941916, 2020). "Here, we sought to ascertain the relevance of SOX9 transcription factor as a prognostic marker in gastric cancer." (PMID 31275454, 2019). "In gastric cancer cells, SOX9 promotes EMT by activating the Hippo-YAP pathway and SOX9 silencing rescued the expression of E-cadherin and downregulated mesenchymal markers N-cadherin, vimentin and SNAIl." (PMID 31547193, 2019). "Although there was a trend for an increased frequency of gastric cancer samples expressing SOX9 when β-catenin was expressed in the nucleus, this difference was not statistically significant." (PMID 31275454, 2019). "Despite possible limitations, our results are based in one of the largest tumour series used so far to assess the clinical relevance of SOX9 in gastric cancer and the more complete one regarding clinicopathological features, survival data, and treatment data." (PMID 31275454, 2019). "In the present study, we use TMA technology to evaluate the clinical significance of SOX9 expression in a large consecutive series of primary gastric cancer from Northern Portugal." (PMID 31275454, 2019). "In conclusion, we have identified SOX9 as a biomarker of disease relapse in gastric cancer patients." (PMID 31275454, 2019).
gastric cancer (continued). "In 83% (275/333) of the gastric carcinoma cases, SOX9 was located in the nucleus and frequently showed a strong staining pattern." (PMID 31275454, 2019). "We find nuclear expression of SOX9 in 83% of the gastric carcinoma cases from a Portuguese cohort of 333 patients with both clinicopathological and survival data." (PMID 31275454, 2019). "For that, we studied SOX9 expression by immunohistochemistry in a consecutive, single-hospital patient series of primary gastric carcinomas." (PMID 31275454, 2019). "Aim of this study was to investigate the prognostic value of ECG and its association with a stem cell like phenotype indicated by expression of the transcription factor SOX9 in gastric cancer." (PMID 29703178, 2018). "The results showed that Reg IV and SOX9 proteins were expressed in both gastric cancer and adjacent tissues." (PMID 29587675, 2018). "The mRNA expression levels of Reg IV and SOX9 were measured by real-time PCR in the 93 cases of gastric cancer and their paired normal tissues." (PMID 29587675, 2018). "Third, Reg IV protein and transcript expression level both had a positive correlation with SOX9 protein and transcript expression in gastric cancer." (PMID 29587675, 2018). "In this study, we revealed that Reg IV and SOX9 were both overexpressed in human gastric cancer tissues, and the Reg IV transcript and protein expression demonstrated a positive correlation with the SOX9 transcript and protein expression." (PMID 29587675, 2018). "The regulatory mechanism involving Reg IV and SOX9 in gastric cancer needs to be further investigated." (PMID 29587675, 2018). "Reg IV expression vectors and a siRNA of Reg IV and SOX9 were transfected into human gastric cancer cells and the protein and mRNA levels of Reg IV and SOX9 were investigated by western blot and real-time PCR." (PMID 29587675, 2018). "Further studies revealed that overexpression of SOX9 is related to the progression of gastric cancer, and the level of SOX9 methylation increases during progression and decreases in the tumorigenesis of gastric cancer." (PMID 29587675, 2018). "Similar, in gastric cancer SOX9 over-expression is related to tumour progression and associated with lower 5-year survival, tumour invasion as well as advanced TNM category." (PMID 29703178, 2018). "Our study demonstrated that Reg IV positively regulates the expression of SOX9 and is involved in tumor cell invasion and migration in gastric cancer." (PMID 29587675, 2018). "From the fact that cases with extracapsular growth show higher SOX9 expression it can be concluded that ECG is a promising biomarker for a more aggressive gastric cancer phenotype." (PMID 29703178, 2018). "Fifth, overexpression of Reg IV significantly promoted SOX9 protein expression in both gastric cancer cells." (PMID 29587675, 2018). "We performed IHC analysis to examine Reg IV and SOX9 protein expression in 102 gastric cancer tissues and 40 paired adjacent tissues stained with Reg IV and SOX9 antibody." (PMID 29587675, 2018). "Reg IV and SOX9 are both overexpressed and Reg IV expression has a positive correlation with SOX9 expression in gastric cancer." (PMID 29587675, 2018). "The Reg IV and SOX9 protein expression levels were both significantly higher in gastric cancer tissues compared with adjacent tissues (p = 0.022, p = 0.003)." (PMID 29587675, 2018). "The results showed that Reg IV potentiated invasion and migration by modulating SOX9 expression, and there was a feedback effect between Reg IV and SOX9 in gastric cancer cells." (PMID 29587675, 2018). "This is supported by the fact that ECG correlates with the expression of SOX9 indicating that this biomarker probably plays an important role in the pathogenesis of gastric cancer and ECG formation." (PMID 29703178, 2018). "The invasion and migration ability of gastric cancer cells with overexpressed Reg IV and with gene silence of Reg IV and SOX9 were examined by transwell chambers and wound healing assay." (PMID 29587675, 2018).
gastric cancer (continued). "Expression of Reg IV and SOX9 were investigated by immunohistochemistry (IHC) and real-time PCR, and the correlation between the expression of Reg IV and SOX9 was analyzed in gastric cancer tissues." (PMID 29587675, 2018). "Aberrant SOX9 expression contributes to the development of gastric cancer by inactivation of GKN1 as an early event." (PMID 29348895, 2017). "SOX9 is shown to be required in migration and in invasion of uroepithelial carcinoma cells in vitro, and upregulation of SOX9 is related to the progression of prostate and gastric cancers." (PMID 23687991, 2013). "This study identifies the SOX9/TIMP1 axis as a key regulator of immune evasion in gastric cancer." (PMID 41270217, 2026). "Strikingly, both CDK1 and SOX9 were upregulated in cisplatin-resistant gastric cancer cell lines." (PMID 41063222, 2025). "It was also reported that SOX9 could activate the Wnt/β-catenin pathway to drive the growth and metastasis of gastric cancer." (PMID 37328795, 2023). "Meta-analysis of SOX9 expression and clinicopathological features in gastric cancer." (PMID 36123852, 2022). "The association of SOX9 expression with MUC2 (an intestinal differentiation marker) expression is consistent with its role in Helicobacter pylori infection and overrepresentation of intestinal-type histology in Helicobacter pylori-related gastric cancers." (PMID 35221802, 2022). "Additionally, SRY-box transcription factor 9 (SOX9) knockdown upregulated REG4 protein expression in gastric cancer cells; a positive correlation of REG4 expression with SOX9 expression in gastric cancer was noted." (PMID 36172286, 2022). "SOX9 is a potential prognostic marker in gastric cancer (GC) patients." (PMID 36123852, 2022). "The prognostic value of SOX9 expression for overall survival in gastric cancer." (PMID 36123852, 2022). "Numerous studies demonstrated that TGF-β1 could regulate SOX9 in the gastric cancer cell, kidney, and atrial fibroblasts, while another study showed that SOX9 could upregulate TGF-β1 expression in hepatic tissue of mice after IR injury." (PMID 35586685, 2022). "Previous studies showed that CDX2 may be an upstream regulator of Reg IV expression in gastric cancer, and our previous report showed that Reg IV upregulated SOX9 expression and enhanced cell migration and invasion in gastric cancer cells." (PMID 33639844, 2021). "Moreover, miR-613 mimic elevated cell sensitivity to cisplatin by down-regulating SOX9 in gastric cancer." (PMID 33969374, 2021). "SOX9 acts as a downstream target of Yes-associated protein 1 (YAP1), which could enhance epithelial-mesenchymal transition (EMT) in gastric cancer and induce cancer stem cell properties in esophageal cancer through the Hippo-YAP pathway." (PMID 35201494, 2021). "In addition, SOX9 and miR-520f-3p expression were significantly reversely correlated with one another in gastric cancer tissues (Spearman’s r = −0.5626, P < 0.05)." (PMID 32277152, 2020). "In line with this, tumors derived from MKN45 gastric cancer cells and U373 glioma cells with overexpression of SOX9 presented a markedly higher number of Ki67 positive cells than those tumors formed by control cells in vivo, together demonstrating that SOX9 regulates cancer cell proliferation." (PMID 31941916, 2020). "As such, this suggests the possibility that targeted therapies modulating the miR-520f-3p/SOX9 pathway could offer novel opportunities to improve gastric cancer patient survival." (PMID 32277152, 2020). "Almost all gastric carcinoma cells overexpressed the stem cell marker SOX9." (PMID 33362856, 2020).
gastric cancer (continued). "Our specific aims were to assess the value of SOX9 expression as a prognostic marker using two clearly defined outcomes—patient overall survival and time to relapse—and as a predictive marker of response to therapy in gastric cancer patients." (PMID 31275454, 2019). "We anticipate that SOX9 expression could be an important biomarker for the prediction of relapse in gastric cancer stratifying patients to different surveillance schemes or treatment options." (PMID 31275454, 2019). "We suggest that SOX9 might be used as a prognostic marker of tumour relapse in gastric cancer patients, which is very important at the clinical level due to the extent of relapse in this type of tumour, even in early stage disease." (PMID 31275454, 2019). "The apparent contradiction between results obtained in vitro and the prognostic value we determined in our study suggests a complex role of SOX9 in gastric cancer that might be context and dose-dependent." (PMID 31275454, 2019). "In vitro studies demonstrated malignant properties of high levels of SOX9 in gastric cancer cells." (PMID 31275454, 2019). "In order to evaluate whether SOX9 expression in gastric cancer correlated with the patient outcome, Kaplan-Meier curves were constructed, using two clearly defined end-points: time to relapse (disease-free survival) and overall survival." (PMID 31275454, 2019). "As our data show a significant correlation between ECG and the marker SOX9, it could be assumed from our data that ECG may be associated with stemness properties in gastric cancer." (PMID 29703178, 2018). "Moreover, SOX9 was identified as one of the downstream targets of Reg IV on GeneChip analysis in gastric cancer." (PMID 29587675, 2018). "Reg IV may regulate the SOX9 expression and participate in the invasion and metastasis of gastric cancer." (PMID 29587675, 2018). "Reg IV siRNA significantly inhibited SOX9 expression in both gastric cancer cells." (PMID 29587675, 2018). "Nevertheless, it remains controversial, whether SOX9 is a suitable stem cell marker in gastric cancer." (PMID 29703178, 2018). "Fourth, the Reg IV overexpression could significantly increase the invasion and migration abilities of gastric cancer cells, and the Reg IV siRNA and SOX9 siRNA could both significantly inhibit the invasion and migration abilities of gastric cancer cells." (PMID 29587675, 2018). "Furthermore, high SOX9 expression is associated with advanced TNM category, poorer prognosis and tumour progression, both in gastric cancer and other types of gastrointestinal cancer." (PMID 29703178, 2018). "SOX9 siRNA significantly promoted Reg IV protein expression in both gastric cancer cells." (PMID 29587675, 2018). "Therefore, Reg IV and SOX9 participated in the regulation of tumor invasion and metastasis in gastric cancer." (PMID 29587675, 2018). "To test for universality of SOX9 expression as prognostic factor in other cancers, we additionally analysed unbiased publicly available datasets of breast (n = 3951), ovarian (n = 1306), lung (n = 1926) and gastric cancer (n = 876)." (PMID 29121666, 2017). "However, both aberrant SOX9 expression in carcinoma tissues and elevated SOX9 expression are correlated to disease progression and poor prognosis for hepatocellular carcinoma, gastric cancer and prostate cancer." (PMID 23687991, 2013). "Another well-known stem cell marker, SOX9, has been identified as a marker to predict disease recurrence in patients with gastric cancer (GC)." (PMID 39335106, 2024). "In a similar vein, the exosome-associated circ0032821 promotes oxaliplatin resistance in gastric cancer (GC) cells by regulating SOX9 via miR-515-5p." (PMID 37587333, 2023). "The negative association of SOX9 with PD-L1 suggests gastric cancer with “stem cell features” might be resistant to PD-L1-inhibitor-based immunotherapy." (PMID 35221802, 2022).
gastric cancer (continued). "Therefore, we speculate that CDX2 may regulate the migration and invasion of gastric cancer cells through Reg IV/SOX9 signaling." (PMID 33639844, 2021). "In addition, we show that the absence of SOX9 expression in the tumour is associated with increased risk of relapse in gastric cancer patients." (PMID 31275454, 2019). "Finally, we assessed whether SOX9 expression was predictive of therapy response in gastric cancer patients." (PMID 31275454, 2019). "However, it could be concluded from our data that SOX9 acts as a pro-oncogene in gastric cancer and plays an important role in gastric cancer progression and formation of ECG in lymph node metastasis." (PMID 29703178, 2018). "Reg IV expression may promote tumor invasion and metastasis by regulating SOX9, and better understanding the regulatory mechanism of Reg IV may contribute to the identification of new targets for the diagnosis and treatment of patients with gastric cancer." (PMID 29587675, 2018). "However, studies of SOX9 in gastric cancer are rarely reported." (PMID 29587675, 2018). "We performed cDNA microarray analysis to identify the downstream target genes of SOX2 in gastric cancer cells, and found that many tumor-associated genes exhibited significant changes in expression after SOX2-overexpression (e.g., LTF, PPP2R1B, TGFBR2, SERPINE1, MMP9, HMGA1 and SOX9)." (PMID 21304604, 2011). "In gastric cancer, ENO1 promotes tumor growth 45 by stabilizing the expression of genes such as SOX9, VEGF-α, GPRC5A, and MCL-1." (PMID 40303285, 2025). "Here we present a study on the expression of emerging biomarkers SOX9, MCL-1 and SPOCK1 in a gastric cancer tissue microarray (TMA)." (PMID 35221802, 2022). "Here we studied the expression of emerging prognostic markers SOX9, MCL-1, and SPOCK1 (Testican-1) in a cohort of gastric cancer by immunohistochemistry and investigated how individual biomarkers and their combinations predict disease prognosis." (PMID 35221802, 2022). "SOX9 is a transcription factor which belongs to the SOX family and was induced by Reg IV in MKN-28, MKN-45, and AGS gastric cancer cells." (PMID 33639844, 2021). "Further study suggested that miR-105 was negatively correlated with SOX9, and directly targeted it to suppress cell migration, invasion, and EMT in gastric cancer." (PMID 34299149, 2021). "Recent studies have further shown that SOX9 suppresses antitumor immunity in KRAS-driven lung adenocarcinoma, is correlated with immune-suppressive pathways across cancers, and promotes an immunosuppressive microenvironment in gastric cancer." (PMID 40692865, 2025). "When SOX9 is increased to a certain level, it may conversely suppress the expression of CDX2 and Reg IV, resulting in a reduction of migration and invasion of gastric cancer cells." (PMID 33639844, 2021). "SOX9 nuclear expression was absent in 17% of gastric cancer cases and predicted worse disease-free survival (P = 0.03)." (PMID 31275454, 2019). "Furthermore, we intended to analyse the association of ECG with the protein expression of the embryonic transcription factors SOX9 and SOX2 both being potential biomarkers for a stem cell like phenotype in gastric cancer." (PMID 29703178, 2018). "Absence of SOX9 expression was observed in 17% of gastric carcinoma cases." (PMID 31275454, 2019). "Regardless of the type of cancer, high SOX9 expression levels always and consistently prevailed as strong predictor of poor 5-years relapse free survival (breast), progression-free survival (ovarian cancer) and overall survival (lung and gastric cancer)." (PMID 29121666, 2017). "Thus, we speculate that the aberrant expression of SOX9 may trigger negative feedback regulation on CDX2 and Reg IV in gastric cancer cells." (PMID 33639844, 2021).